WDR7 (WD repeat domain 7)
Synonyms: KIAA0541; TRAG
Tractability: PROTAC: ubiquitination databases record sites on it; its protein half-life has been measured.
Gene: Protein-coding gene on chromosome 18 (56,651,343 to 57,029,811, forward strand). Ensembl gene ENSG00000091157.
Subcellular location (Human Protein Atlas): Nucleoplasm; Cytosol
Gene Ontology:
Biological process: vacuolar acidification
Cellular component: cytoplasm; RAVE complex
Genetic constraint (gnomAD): Loss-of-function variants: 42 observed, 152.53 expected, observed/expected ratio (o/e) 0.28, 90% interval 0.21 to 0.36. The upper end of that interval is the gene's LOEUF score, 0.36, which puts it in group 1 of 6, group 1 being the genes least tolerant of losing a copy. Missense variants: 1,468 observed, 1,851.3 expected, observed/expected ratio (o/e) 0.79, 90% interval 0.76 to 0.83. Synonymous variants: 586 observed, 672.15 expected, observed/expected ratio (o/e) 0.87, 90% interval 0.81 to 0.93.
Homologues: Orthologues: chimpanzee WDR7 (99% identical), macaque WDR7 (99% identical), rabbit WDR7 (98% identical), pig WDR7 (97% identical), dog WDR7 (97% identical), mouse Wdr7 (95% identical), guinea pig WDR7 (95% identical), rat Wdr7 (95% identical), tropical clawed frog wdr7 (87% identical), zebrafish WDR7 (53% identical), Drosophila melanogaster Rbcn-3B (43% identical), Caenorhabditis elegans rbc-2 (33% identical). Paralogues in human: MAPKBP1 (12% identical), WDR62 (11% identical), WDR17 (9% identical), TEP1 (9% identical), NEDD1 (7% identical), WDR75 (7% identical), WDR81 (7% identical), AHI1 (7% identical), POC1B (6% identical), WDR27 (6% identical), SNRNP40 (5% identical), POC1A (5% identical), and 14 more.
Diseases named in the same sentence as WDR7 in open-access papers:
WDR7 is named in the same sentence as 14 diseases in open-access papers, as found by Europe PMC text mining. Sharing a sentence is not in itself a finding about the gene and the disease. The quoted sentences say what the papers report.
breast carcinoma (5 papers, 2015 to 2024). "Therefore, in this study, we aimed to identify the function of GPR30 in breast cancer and the association between WDR7-7 and GPR30 signaling." (PMID 29096683, 2017). "In cell cycle and apoptosis, the expression of the lincRNA-RoR gene increases in breast cancer probably by reducing the expression of WDR7." (PMID 32128092, 2019). "In our preliminary screen of lncRNAs in SKBR3 breast cancer cells, we saw that calycosin increased the expression of several lncRNAs, including WDR7-7, TTC21B-AS1, and CTA-384D8.34." (PMID 29096683, 2017). "After demonstrating the relationship between WDR7-7 and GPR30 expression in breast cancer cells, we investigated the association between the WDR7-7-GPR30 signaling pathway and proliferation in breast cancer cells and the mechanism of this effect." (PMID 29096683, 2017). "Here, we show that calycosin inhibited the proliferation of both ER− (MDA-MB-468 and SKBR3) and ER+ breast cancer cells (MCF-7 and T47D) and that these inhibitory effects were associated with the up-regulation of the long non-coding RNA (lncRNA) WDR7-7." (PMID 29096683, 2017). "Pretreatment with pCDNA3.1-WDR7-7 or WDR7-7 shRNA increased or reduced WDR7-7 levels, respectively, in breast cancer cells." (PMID 29096683, 2017). "Calycosin may have inhibitory effects on ER breast cancer since it at least partially reduces the growth of breast cancer cells through WDR7‐7‐GPR30 signaling." (PMID 38230908, 2024). "Together, these findings suggest that SRC, EGFR, ERK1/2, and Akt, which are key regulators of cell proliferation and survival in breast cancer cells, act as downstream effectors of the WDR7-7-GPR30 pathway, especially in ER− cells due to the absence of an ER-mediated pathway." (PMID 29096683, 2017). "Moreover, the down-regulation of WDR7-7 expression was confirmed in both breast cancer cells lines, including MCF-7, T47D, SKBR3, MDA-MB-468, and MDA-MB-231 cells." (PMID 29096683, 2017). "Additionally, the finding that calycosin inhibited both the miR-375-ERα feedback loop and the WDR7-7-GPR30 pathway in ER+ breast cancer cells may explain why ER+ breast cancer cells seem to be more sensitive to calycosin than ER− breast cancer cells." (PMID 29096683, 2017). "This study also indicates that the expressions of WDR7 and lincRNA-RoR in MDA-MB-231 breast cancer cell line are negatively related." (PMID 32128092, 2019). "We found that silencing WDR7-7 with specific shRNAs increased GPR30 levels in both ER+ (MCF-7, T47D) and ER− breast cancer cells (SKBR3, MDA-MB-468), contributing to the promotion of cell growth (p < 0.05)." (PMID 29096683, 2017). "Since WDR7-7 showed the greatest average increase in expression, we chose to examine the role of WDR7-7 in breast cancer carcinogenesis." (PMID 29096683, 2017). "Meanwhile, we show that calycosin stimulated the WDR7-7-GPR30 signaling pathway in MCF-7, T47D, MDA-MB-468, and SKBR3 breast cancer cells." (PMID 29096683, 2017). "In addition, we examined whether the WDR7-7-mediated regulation of the GPR30 pathway might be involved in the inhibitory effect induced by calycosin on breast cancer cells, especially in ER− breast cancer cells." (PMID 29096683, 2017). "Therefore, we provide evidence that, in addition to the miR-375-ERα feedback loop in ER+ breast cancer cells, a negative relationship between WDR7-7 and GPR30 exists in both ER+ and ER− breast cancer cells." (PMID 29096683, 2017).
viral infection (3 papers, 2020 to 2023). "While it has been established that an acidic endosomal environment is required for IAV entry, we showed that depletion of WDR7, CCDC115, and TMEM199 increases endo-lysosomal acidification, yet reduces viral infection." (PMID 31919360, 2020). "To test if CMTR1 has potential interactions with Xofluza, we pre-treated WDR7, CCDC115, TMEM199, and CMTR1 polyclonal KO cells with increasing doses of Baloxavir (active form of the drug) prior to PR8 virus infection and measured changes in infectivity." (PMID 31919360, 2020). "Many of them, such as WDR7, INPP5E, CDK13, VAPA, NAMPT and PUM2, are known to be involved in viral infection mechanisms, whether at the point of the viral entry into the cell or during viral replication." (PMID 35563619, 2022).
alcohol dependence (1 paper, 2022). Physical and psychological dependence on alcohol. "The most highly connected hub gene of the cyan module was Wdr7, whose altered expression was found in subjects with depression and alcohol dependence comorbidity." (PMID 34848858, 2022).
multiple sclerosis (1 paper, 2010). A progressive autoimmune disorder affecting the central nervous system resulting in demyelination. "We already discussed the role of WDR7 as regulator of genes in the endoplasmic reticulum and the implication of this finding for multiple sclerosis." (PMID 20856902, 2010).
type 2 diabetes (1 paper, 2025). "SNPs in WDR7 have been shown to be associated with type 2 diabetes." (PMID 40025146, 2025). "The lead variant in WDR7 has not be reported to be associated with FI in GWASs; however, other variants in this locus are linked to type 2 diabetes." (PMID 40025146, 2025). "Both WDR7 and BOD1L2 have previously been reported to be associated with type 2 diabetes." (PMID 40025146, 2025).
cancer (4 papers, 2017 to 2024). A tumor composed of atypical neoplastic, often pleomorphic cells that invade other tissues. "Calycosin enhances the effect of TGF-β on apoptosis, which can inhibit the proliferation of cancer cells through WDR7-7-GPR30 signaling." (PMID 35594510, 2022). "The exact functions of lncRNA-RoR and WDR7 genes and their relative expressions in various cancers are not clear." (PMID 32128092, 2019). "Therefore, WDR7-7 and GPR30 may be potential mediators of the anti-cancer activity of calycosin that function alongside traditional estrogen receptors and may serve as additional biological targets in estrogen-sensitive tumors." (PMID 29096683, 2017).
infection (4 papers, 2020 to 2024). The state of being infected such as from the introduction of a foreign agent such as serum, vaccine, antigenic substance or organism. "Similar to previous observation with PR8 and Udorn virus, we showed that A549 cells lacking WDR7, CCDC115, TMEM199 or CMTR1 again displayed lower levels of IAV HA RNA at 16 h post-infection compared to control cells by qRT-PCR." (PMID 31919360, 2020).
tumor (2 papers, 2020 to 2021). "We found two deleted regions shared by both tumor types in three out of the four cell lines H23R, A2780R, and OVCAR3R, but not in H460 cells, located on 18q21.2–18q21.31 and 18q21.32, affecting the genes RAB27B, CCDC68, TCF4, TXNL1, WDR7, and BOD1P; and genes ZNF532, SEC11C, GRP, respectively." (PMID 32224864, 2020).
WDR7 also shares sentences with these, for which no sentence is quoted: amyotrophic lateral sclerosis (3 papers); pancreatic cancer (2); colitis (1); depression (1); influenza infection (1); lung adenocarcinoma (1).